MTHFD2 (methylenetetrahydrofolate dehydrogenase (NADP+ dependent) 2, methenyltetrahydrofolate cyclohydrolase)
Diseases named in the same sentence as MTHFD2 in open-access papers (continued):
Sharing a sentence is not in itself a finding about the gene and the disease.
cancer (continued). "We propose that cancer selectivity of TH9619 is related to the MTHFD2-dependent release of mitochondrial formate, which is a hallmark of cancer cells." (PMID 37012496, 2023). "MTHFD2 was found up-regulated in many cancers and the high MTHFD2 expression level was related to a poor prognosis." (PMID 37484807, 2023). "The results demonstrated moderate or high levels of MTHFD2 protein expression in most cancers except for those of the pancreas, kidney, and ovary." (PMID 36726381, 2023). "This study discovered that drugs targeting MTHFD1 can kill cancer cells that have upregulated MTHFD2, revealing cancer vulnerabilities that can be exploited for drug development." (PMID 37012496, 2023). "TH9619 imposes a cytostatic effect on cancer cells with low MTHFD2 expression by restricting the pool of purines available for DNA synthesis." (PMID 37012496, 2023). "Recent studies have led to the development of chemical inhibitors specifically targeting SHMT2 and MTHFD2, potentially promising as treatments to impair proliferation and aggressiveness of cancer cells." (PMID 36964165, 2023). "MTHFD2 is one of the most differentially expressed metabolic enzymes in cancers and is involved in DNA replication and genomic stability of cancer cells." (PMID 37664062, 2023). "Folate cycle enzymes, especially MTHFD2, a folate cycle enzyme, is overexpressed in various cancer cells and enable cancer cells to become more tolerant to effector T cells." (PMID 39872059, 2023). "Pan-cancer analysis was performed to have a basic understanding of the biological functions and prognostic value of MTHFD2." (PMID 38130721, 2023). "Inhibition of the MTHFD2 enzyme reduces tumour growth, migration, invasion, and proliferation and promotes cell death, chemosensitivity and differentiation in various cancer cells." (PMID 37872243, 2023). "It is reported that the level of MTHFD2 enzyme is increased in various types of cancers, developing embryos, and transformed cells, but its detection is low or minimal in the normal healthy cells." (PMID 37872243, 2023). "We here propose that MTHFD2 supports formate overflow in cancer cells rendering them sensitive to MTHFD1(DC) inhibition by TH9619." (PMID 37012496, 2023). "RNA sequencing data from The Cancer Genome Atlas (TCGA) was applied to analyze the immunological roles and prognostic value of MTHFD2 in pan-cancers." (PMID 38130721, 2023). "For instance, MTHFD2 can induce immune escape of cancer cells by promoting the expression of basal and IFN-γ-stimulated PD-L1." (PMID 37342762, 2023). "The pan-cancer co-expression analysis revealed that MTHFD2 was positively correlated with most immunoregulators, including immune checkpoints, in most cancers." (PMID 38130721, 2023). "Serine supports purine synthesis through a single-carbon metabolic pathway as a carbon donor, of which methylenetetrahydrofolate dehydrogenase (MTHFD2) is a major enzyme that is frequently overexpressed in human cancers." (PMID 37337630, 2023). "Considering the important role of miRNAs in regulating gene expression in various cancers, we finally found hsa-miR-455-5p as the potential upregulation miRNA targeting MTHFD2 in EC via correlation analysis, expression analysis, and survival analysis together." (PMID 37484807, 2023). "Methylenetetrahydrofolate dehydrogenase 2 (MTHFD2) is a mitochondrial one-carbon (1C) metabolism enzyme that is overexpressed in cancer cells and barely expressed in most healthy adult tissues." (PMID 37936908, 2023). "DS18561882 is a small molecule inhibitor of MTHFD2 that has been shown to inhibit cancer cell growth and T-cell-mediated inflammation in vivo." (PMID 37986788, 2023).
cancer (continued). "The mitochondrial isoforms of folate cycle enzymes serine hydroxymethyl transferase and methylene-tetrahydrofolate reductase (SHMT2 and MTHFD2) are very important targets for drug development in cancer therapy." (PMID 37233697, 2023). "TH9619 is a potent inhibitor of dehydrogenase and cyclohydrolase activities in both MTHFD1 and MTHFD2, and selectively kills cancer cells." (PMID 37012496, 2023). "Methylenetetrahydrofolate dehydrogenase 2 (MTHFD2), whose aberrant expression is common in cancers, has recently been identified as a potential regulator of immune response." (PMID 38130721, 2023). "The association of MTHFD2 with several immunological features of tumor microenvironment (TME), including cancer-immunity cycle, immune cells infiltration, immune checkpoints expression, and T cell inflamed score was analyzed in TCGA-BLCA cohort." (PMID 38130721, 2023). "In this study, we briefly assessed the prognostic value and immunological function of MTHFD2 in pan-carcinoma, and further investigated its relationship with TME, molecular subtypes, and immunotherapy response in BLCA in detail." (PMID 38130721, 2023). "A particular interest has been generated in the MTHFD2 enzyme as it is oncofetal, being expressed during early embryogenesis, silenced in adult cells and then re‐expressed in transformed cancer cells, making it an attractive anticancer target." (PMID 35583750, 2022). "Our follow-up studies interrogated the molecular mechanisms of MTHFD2 in UCB to find a potential anti-cancer target." (PMID 35581573, 2022). "By exploiting this structurally less conserved allosteric site of MTHFD2, we would be able to develop new inhibitors to help cancer patients." (PMID 35613161, 2022). "Mechanism studies indicate that MTHFD2 serves as a rate limiting enzyme providing sufficient purine nucleotides which are DNA precursors required by the rapid growth of cancer cells." (PMID 35790743, 2022). "As MTHFD2 generates metabolites to sustain biomass production in cancer, we supplemented metabolites to MTHFD2 knockdown cells to identify potential rescue." (PMID 35228749, 2022). "Taken together, these data show enhanced selectivity of MTHFD2 inhibitors toward MTHFD2-expressing cancer cells with a wide therapeutic index." (PMID 35228749, 2022). "Collectively, these results confirm the proposed mechanism of action for MTHFD2 inhibitors via induction of RS and provide rational support for the potential future use of MTHFD2 inhibitors as cancer-selective sensitizers to ATR-signaling blockade therapies." (PMID 35228749, 2022). "It has been proposed that MTHFD2L functions to maintain a baseline activity of mitochondrial folate metabolism, while MTHFD2 is upregulated in conditions where greater flux through the pathway is required, such as during embryogenesis or in cancer cells." (PMID 35712863, 2022). "Serine hydroxymethyltransferase 2 (SHMT2) and MTHFD2 were indeed among the most overexpressed metabolic genes in nineteen different cancer types analyzed." (PMID 35831624, 2022). "The widespread reactivation of MTHFD2 in tumors suggests an isoform switch from MTHFD2L to MTHFD2 during cancer transformation." (PMID 35228749, 2022). "As MTHFD2 is one of the most upregulated metabolic enzymes in cancer, it has generated a lot of interest as a potential anticancer target." (PMID 35583750, 2022). "We show that both MTHFD2 RNAi knockdown and MTHFD2 inhibitors kill cancer cells through depletion of thymidine, resulting in misincorporation of uracil and RS, which induces cell death in cancer, but not in nontumorigenic cells." (PMID 35228749, 2022). "Other genes that are differentially expressed in Bhas 42 CTA by TPA treatment include RAN, MTHFD2, WT1, and AURORA-A, which are markers that cause cancer formation and malignant transformation in humans and laboratory animals." (PMID 35328637, 2022).
cancer (continued). "During early embryogenesis and in transformed cells, the mitochondrial dehydrogenase and cyclohydrolase activities are instead carried out by the MTHFD2 enzyme, suggesting an isoform switch from MTHFD2L to MTHFD2 during cancer transformation." (PMID 35583750, 2022). "In the present study, we present new MTHFD2 inhibitors that selectively kill cancer cells through thymine-less death, representing a promising therapeutic approach in cancer." (PMID 35228749, 2022). "MTHFD2 was overexpressed in various cancer cells and further elevated by IFN-γ, enhancing PD-L1(CD274) production at basal and IFN-induced levels." (PMID 35693982, 2022). "It is clear from the literature that MTHFD2 RNAi depletion is highly effective in killing most cancers." (PMID 35583750, 2022). "The bifunctional methylenetetrahydrofolate dehydrogenase (NADP+ dependent) 2, methenyltetrahydrofolate cyclohydrolase (MTHFD2) has been reported to play an oncogenic role in various types of cancers." (PMID 35581573, 2022). "The regulatory factors and mechanisms of elevated MTHFD2 expression in various cancer types need to be clarified, since MTHFD2 is a promising novel target for anti-cancer therapy." (PMID 35581573, 2022). "Overexpression of MTHFD2 provides cancer cells with the necessary building blocks for nucleotide (purine and pyrimidine) biosynthesis during rapid proliferation." (PMID 35613161, 2022). "There are numerous reports supporting that MTHFD2 is required for survival in various cancers using RNAi approaches or small molecule inhibitors." (PMID 35583750, 2022). "We noticed that cancer immunotherapy by PD1 blockade pathway was considerably enriched in MTHFD2 high expression group by GSEA." (PMID 35581573, 2022). "Our work sheds new light on the structural and kinetic framework of MTHFD2, which will be helpful to design small molecule inhibitors that can be used for cancer treatment." (PMID 35613161, 2022). "The tool compound TH7299, as well as two of the most promising candidates, TH9028 and TH9619, were chosen to investigate the MTHFD2 mechanism of action and cancer biology." (PMID 35228749, 2022). "Clearly, these preliminary observations that MTHFD2 inhibitors induce differentiation require attention in future studies, especially in the context of tumors characterized by elevated numbers of cancer stem cells, where relapse is common." (PMID 35228749, 2022). "Overexpression of MTHFD2 was indicated in gefitinib resistant LUAD and associated with cancer stem-like properties." (PMID 35790743, 2022). "Methylenetetrahydrofolate dehydrogenase/cyclohydrolase (MTHFD2) is a new drug target that is expressed in cancer cells but not in normal adult cells, which provides an Achilles heel to selectively kill cancer cells." (PMID 35613161, 2022). "Overall, these results demonstrate a functional link between MTHFD2-dependent cancer metabolism and replication stress that can be exploited therapeutically with this new class of inhibitors." (PMID 35228749, 2022). "Although the folate cycle can occur in both the cytoplasm and the mitochondria, cancer cells typically overexpress mitochondrial 1C metabolism enzymes, such as MTHFD2 and SHMT2, linking mitochondrial folate metabolism to cancer progression." (PMID 33946927, 2021). "Given that the SHMT2 and MTHFD2 genes are attractive targets for cancer therapy, small-molecular inhibitors have been developed to target the folate pathway of 1C metabolism, some of which have been studied in preclinical and clinical trials." (PMID 34298902, 2021). "In the proliferating daughter cancer cells, the inhibition of 1C enzymes in mitochondria, Shmt2 and Mthfd2, is supposed to induce tumor eradication." (PMID 34298902, 2021). "Unexpectedly, meanwhile, MTHFD2 was dramatically promoted by IFN-γ in all these cancer cells or moderately elevated in SW1990, probably due to the high basal level." (PMID 33782411, 2021).
cancer (continued). "Surprisingly, MTHFD2L exhibited a greater increase in cancer tissue versus normal tissue in AML compared to MTHFD2." (PMID 33707653, 2021). "Whereas MTHFD2 is considered a tumor-selective target, a recent study reported that normal and cancer cells express both MTHFD2 and MTHFD2L." (PMID 35008360, 2021). "Stimulation by growth factors can lead to the proliferation of cancer cells, and in parallel with the upregulation of the MTHFD2, which further drives cancer cell proliferation independently of its dehydrogenase activity." (PMID 34231329, 2021). "MTHFD2 was overexpressed in various cancer cells and further induced by IFN-γ, which promotes both basal and IFN-γ-induced PD-L1 expression." (PMID 33782411, 2021). "Methylenetetrahydrofolate dehydrogenase 2 (MTHFD2), a mitochondrial enzyme of one‐carbon metabolism, has been reported to be dysregulated in many cancers." (PMID 34121323, 2021). "A recent study demonstrated that mTORC1 signaling in cancer cells increases metabolic flux though purine synthesis via expression of MTHFD2." (PMID 33468252, 2021). "The MTHFD2 gene is upregulated in variouscancers but very low or undetectable in normal proliferating cells,and therefore a potential target for cancer treatment." (PMID 34337952, 2021). "A T cell cytotoxicity assay based on LDH release or Real-Time-Cell-Index analysis showed aggravated cytolysis in MTHFD2 KD or KO cancer cells, which was significantly reversed by the exogenously expressed PD-L1." (PMID 33782411, 2021). "Having uncovered its relationship with MTHFD2 and PD-L1 in cultured cancer cells, we next wished to confirm the clinical relevance of these associations." (PMID 33782411, 2021). "A previous study showed that MTHFD2 is broadly required for cancer cell proliferation and viability." (PMID 34231329, 2021). "In agreement with the previously identified role of folate cycle, in MTHFD2-depleted cancer cells, a substantial portion of altered metabolites were nucleosides or nucleoside derivatives; moreover, serine accumulated and SAM decreased." (PMID 33782411, 2021). "The findings are important given the increased interest in targeting mitochondrial metabolism for cancer therapies, and the ongoing efforts for both the development of MTHFD2 inhibitors and of more potent derivatives of β-lap." (PMID 33262939, 2020). "Cell line-derived xenograft and PDX-based studies further supported the anti-cancer effects of MTHFD2 knockdown in vivo." (PMID 32411609, 2020). "As for TUBB6 and MTHFD2, two and seven unique analyses of data with statistical significance revealed higher expression levels in cancer tissues than in normal tissues." (PMID 33193654, 2020). "Several reports have demonstrated MTHFD2 as a critical player in cancer survival related to nucleotide synthesis, NADPH production, and redox defense." (PMID 32411609, 2020). "MTHFD2 has attracted increasing interests in cancer research due to its specific expression pattern and prognostic value." (PMID 32411609, 2020). "The anti-tumor efficacy of these selective MTHFD2 inhibitors in different cancers awaits further assessment." (PMID 32411609, 2020). "The folate-coupled metabolic enzyme MTHFD2 (the mitochondrial methylenetetrahydrofolate dehydrogenase/cyclohydrolase) confers redox homeostasis and drives cancer cell proliferation and migration." (PMID 32811824, 2020). "For example, the mitochondrial folate pathway is significantly upregulated in cancer tissues; in particular, the MTHFD2 enzyme is highly expressed in a number of cancer types, and is correlated with lower survival rates among breast cancer patients." (PMID 32457801, 2020). "This was also validated in our results demonstrating suppressed levels of NADPH in MTHFD2-knockdown cancer cell lines." (PMID 32759461, 2020). "Firstly, MTHFD2 is upregulated in various cancers, transformed cells, and developing embryos, but has low or undetectable level in most differentiated normal adult tissues." (PMID 32411609, 2020).
cancer (continued). "The results showed that MTHFD2 protein and mRNA levels were increased in tumors and cancer cell lines." (PMID 33168819, 2020). "Taken together, this study suggested that MTHFD2-mediated 1C metabolism contributed to cancer stem-like properties and resistance to chemotherapy drugs through the consumption of AICAR." (PMID 32411609, 2020). "A meta-analysis also found that SHMT2 and its downstream enzyme MTHFD2 were broadly required for cancer cell proliferation and viability." (PMID 33066813, 2020). "Understanding how MTHFD2 is involved in cellular redox balance is important to effectively develop therapeutics targeting this enzyme for cancer treatment." (PMID 32811824, 2020). "Given the expression pattern of MTHFD2 and its knockdown effects in various cancers, there is a strong rationale for developing selective inhibitors targeting this enzyme for cancer therapy." (PMID 32411609, 2020). "Concomitantly, MTHFD2 conferred drug resistance and cancer stem-like properties by depleting the intracellular pool of the purine intermediate AICAR, which contributed to the decrease in stemness and increase in drug sensitivity." (PMID 30532069, 2019). "In this study, we demonstrated that MTHFD2-mediated mitochondrial 1C metabolism plays critical roles in cancer cell growth and confers drug resistance and cancer stem-like properties, which are thought to be responsible for tumor recurrence and poor prognosis." (PMID 30532069, 2019). "Some cancer cells with acquired resistance to gefitinib showed increased dependence on MTHFD2, as evidenced by the increase in MTHFD2 expression." (PMID 30532069, 2019). "To explore the molecular mechanisms that determine how MTHFD2 confers drug resistance and stem-like properties to cancer cells, we focused on AICAR, because it was the metabolite that showed the greatest increase upon MTHFD2 knockdown." (PMID 30532069, 2019). "Activation of the EGFR tyrosine kinase induces MTHFD2 expression in some cancer, as well as normal epithelial cells." (PMID 30532069, 2019). "In present study, MTHFD2 was enhanced in most cancer types, indicating its potential as a drug discovery target in most cancers." (PMID 30582043, 2018). "MTHFD2 is highly induced in many cancers and is essential for mitochondrial one-carbon metabolism—the highest scoring metabolic pathway across human cancers." (PMID 29895827, 2018). "It was reported that MTHFD2 is involved in proliferation, metastasis, stemness, and chemoresistance in cancer cells, and suppression of MTHFD2 reduces the malignancy." (PMID 30582043, 2018). "Knockdown of MTHFD2 can inhibit cancer cell proliferation in vitro and reduces (but does not abolish) tumor growth in vivo." (PMID 30275950, 2018). "Analysis of the clinical data indicated that MTHFD2 was enhanced in most cancers compared with normal tissues, and affected the prognosis in cancer patients." (PMID 30582043, 2018). "MTHFD2 expression was compared between primary tumor and normal tissue in various cancers using TCGA data to determine the specificity of MTHFD2 in cancer cells." (PMID 30582043, 2018). "Methylenetetrahydrofolate dehydrogenase 2 (MTHFD2) was reported to be specifically enhanced in cancer." (PMID 30582043, 2018). "The folate-coupled metabolic enzyme MTHFD2 is overexpressed in many tumor types and required for cancer cell proliferation, and is therefore of interest as a potential cancer therapeutic target." (PMID 30275950, 2018). "Since MTHFD2 is differentially upregulated in cancer tissue, it presents an attractive target for anti-cancer compounds." (PMID 29142318, 2017). "Because MTHFD2 is highly expressed in many cancer types, we sought to determine the cofactor preference of this enzyme." (PMID 29225823, 2017). "Their impact on cancer-related metabolism is very high; moreover, SHMT2 and MTHFD2 are preferentially expressed in quickly proliferating cells including cancer." (PMID 28177894, 2017).